CCL22 (C-C motif chemokine ligand 22)
Diseases named in the same sentence as CCL22 in open-access papers (continued):
Sharing a sentence is not in itself a finding about the gene and the disease.
asthma (continued). "Moreover, levels of CCL22 and IL‐1 were significantly higher in acute asthma compared to stable asthma." (PMID 39508721, 2024). "M2a macrophages expressing CD206 and MHCII are associated with asthma severity, and M2a macrophages expressing CCL17 and CCL22 induce the activation of T helper type 2 cells and initiate the infiltration of eosinophil in the lungs by secreting high levels of IL-5 and IL-13." (PMID 37181813, 2023). "Likewise, IL-25 is elevated in asthma and improves mitophagy and CCL-22 secretion in monocytes; moreover, inhibition of mitophagy by PINK1 knockdown reduces the production of CCL-22." (PMID 37181813, 2023). "It is thus strongly assumed that locally enhanced levels of CCL22 in the respiratory tract, as for instance observed in patients diagnosed for idiopathic pulmonary fibrosis or allergic rhinitis and in experimental asthma models, are able to promote pulmonary ILC2 recruitment." (PMID 34177944, 2021). "CCR4 and its ligands (CCL17 and CCL22) play important roles in asthma inflammation." (PMID 33265990, 2020). "Additionally, we observed an increased risk of asthma with elevated concentrations of IL-1RA, and to some extend with EGF, and CCL22." (PMID 31217483, 2019). "Furthermore, in a murine asthma model, CCL22 or CCL17 neutralization decreased eosinophilic airway inflammation and ameliorated allergic symptoms." (PMID 30405619, 2018). "Studies of endobronchial biopsy specimens and BAL fluid of subjects with severe asthma have shown that asthma is associated with elevated bronchial mucosal expression of TSLP and Th1-attracting (IP-10/CXCL10) and Th2-attracting (TARC/CCL17, MDC/CCL22) chemokines." (PMID 22523502, 2012). "However, it remains unclear whether STAT6 and/or NF‐κB influence the development of pulmonary CCL17 and CCL22 in the context of rhinovirus (RV) infection and asthma." (PMID 39508721, 2024). "The significance of CCL22 and CCL17 is further affirmed in murine models of asthma, where the utilization of specific neutralising antibodies enables the reduction of airway hyperresponsiveness and allergic inflammation." (PMID 40577410, 2025). "In most cases, UPM exposure upregulated gene expression or remained unchanged except for CCL22 and RMDN2-AS1 for all groups and CYP1B1 and LINC02029 for the controls and asthma, which were suppressed in almost all tested combinations." (PMID 36012391, 2022). "A recent study using a humanized model of asthma showed a critical role for DC-derived CCL17 and CCL22 in attracting Th2 cells and inducing airway inflammation." (PMID 22125604, 2011). "Additionally, we examined the levels of inflammatory cytokines in sputum and found that IL‐5, IL‐6, IL‐8, TNF‐α, IFN‐γ, CCL17, CCL22, CXCL10, CCL4, CCL2, IL‐4, IL‐13, and CCL26 were significantly lower in stable asthma than in acute asthma." (PMID 39508721, 2024). "Among the genes that were induced in all subjects except for patients with asthma were interferon involved genes (IL28B, IFNAR1), CCL22, and FOSL1 with respect to the upper airways, and several interferon involved genes (IRF3, IFNAR1, IFNB1, IFNGR1, IL28B) in the lower airways." (PMID 24475887, 2014). "In addition to CCL11/eotaixn-1 and TNF-alpha, HBEC exposed to TSLP induced the secretion of CCL22/MDC and CCL17/TARC, two CCR4-ligands that are considered critical Th2-related chemokines in asthma exacerbations." (PMID 25546419, 2014). "An in vivo study was run in the A. fumigatus chronic fungal asthma model to determine whether any difference in neutralizing activity could be seen based on targeting either CCL17 alone or targeting both CCL17 and CCL22." (PMID 24339934, 2013). "The serum levels of TNF‐α (p = 0.025), IFN‐γ (p = 0.011), CCL22 (p = 0.022), IL‐12p70 (p = 0.021), CXCL10 (p = 0.028), CCL2 (p = 0.028), CCL13 (p = 0.024), IL‐4 (p = 0.026), IL‐13 (p = 0.024), and CCL11 (p = 0.028) were found to be downregulated in stable asthma when compared to acute asthma." (PMID 39508721, 2024).
asthma (continued). "The levels of interferon‐γ (IFN‐γ), tumor necrosis factor‐a (TNF‐α), chemokine CCL22 (CCL22), interleukin 12 (IL‐12), chemokine CCL4 (CCL4), chemokine CCL2 (CCL2), and chemokine CCL13 (CCL13)were significantly higher in the acute asthma group than in the stable asthma group." (PMID 39508721, 2024). "Furthermore, HZ-1127 dramatically inhibits TSLP-dependent STAT5 activation and is more potent than Tezepelumab, which is an FDA-approved humanized mAb against TSLP for severe asthma treatment in inhibiting TSLP-induced CCL17 and CCL22 chemokines secretion in human peripheral blood mononuclear cells." (PMID 38566968, 2024). "An obvious potential caveat of total CCR4 blockade as an asthma treatment is the potential for the impairment of regulatory T cell recruitment, since T-regulatory cells (Tregs) have been shown to express CCR4 and to migrate in vitro in response to both CCL17 and CCL22." (PMID 25981299, 2015). "The mechanism could explain why Th2 cells migrate to asthma airways as T cells in bronchial mucosal or bronchoalveolar lavage fluid (BALF) of allergic asthma express CCR4, and meanwhile the levels of CCL22 in BALF but not Th1-selective chemokines are increased upon allergen challenge to the lung." (PMID 35000593, 2022).
ovarian carcinoma (32 papers, 2011 to 2025). A malignant neoplasm originating from the surface ovarian epithelium. "TAMs of ovarian carcinoma patients secrete C-C motif chemokine ligand 22 (CCL22) to recruit Tregs, which is associated with reduced survival rate of the patients." (PMID 34359674, 2021). "One group has shown that in human ovarian cancer, tumor-associated microphages produce chemokine CCL22, which mediates Treg cell trafficking." (PMID 29037250, 2017). "The ovarian cancer environment caused migration of CTLA4+ FOXP3+ GITR+ Tregs via the chemokine CCL22, secreted by tumor cells and TAMs, and its receptor CCR4, expressed by infiltrating Tregs." (PMID 28275576, 2017). "IL10 suppresses proinflammatory cytokine secretion, antigen presentation and CD4+ T cell activation and CCL22 is associated with regulatory T-cell migration in ovarian cancer." (PMID 28266500, 2017). "It has been reported that production of the chemokine CCL22 is associated with human ovarian cancer and has also been observed in other types of malignancies, such as gastric cancer, Hodgkin’s lymphoma, and breast cancer." (PMID 23533029, 2013). "It has also been shown that human ovarian cancer cells and tumor-associated microphages produce chemokine CCL22, which mediates TReg cells trafficking to tumor." (PMID 22481922, 2012). "In human ovarian carcinoma, tumor cells and tumor-associated macrophages were shown to produce a Treg-specific chemokine CCL22, which resulted in the specific recruitment of Treg to the tumor microenvironment via their CCR4 receptor." (PMID 22112546, 2011). "Since T cells expressing CCR4 can respond to chemoatractants (CCL22) secreted by ovarian cancer cells, and CCR4+ Treg have been associated with enhanced tumour recurrence, it may be further timely to address the effect of first line treatment on their frequencies." (PMID 24213326, 2012). "Clinical studies have also confirmed that CD4 + CD25 + Tregs are recruited to tumor sites by recombinant human C-C motif chemokine 22 protein (CCL22) secreted by ovarian cancer cells, resulting in the accumulation of CD4 + CD25 + Tregs in cancer tissues." (PMID 40587482, 2025). "Strikingly, these pre-activated CTLs reduced CCL22 expression in ovarian cancer ascites, compared to the levels spontaneously produced by the ascites cells." (PMID 41142824, 2025). "An increased expression of CCL17 and CCL22 is consistent with the prognosis for patients with colon, lung, and ovarian cancers—the higher the expression of these chemokines in these tumors, the better the prognosis." (PMID 33182504, 2020). "Mice inoculated with ovarian cancer cell lines expressing CCL22 accumulate CCR4+ nTreg, which are blocked by administration of anti-CCR4 mAb, further inhibiting tumor size and progression." (PMID 31681327, 2019). "For example, Curiel at al. demonstrated that CCL22 secreted by TAMs recruits CCR4+ nTregs to promote the formation of immunosuppressive microenvironment inhuman ovarian cancer." (PMID 31629410, 2019). "In human ovarian carcinoma, CCL22 produced by TAMs mediates trafficking of CCR4+ nTreg cells to the tumor and foster immune privilege." (PMID 31629410, 2019). "For instance, an anti-CCR4 antibody mAb2-3 blocks Treg migration and stimulates IFNγ secretion by CD8+ T cells, eventually enhancing anticancer response in an experimental model bearing CCL22-secreting ovarian cancer cells." (PMID 28929459, 2018). "Through the release of CCL22, TAMs attract Tregs to ovarian cancer cell clusters, which in turn suppress cytotoxic T cells." (PMID 28275576, 2017). "For example, a study found that CCR4+ Tregs migrate to the tumor tissue through CCL22 secreted by ovarian cancer cells." (PMID 28388539, 2017). "The plasma CCL22 levels in patients with FIGO stage IV of ovarian cancer was significantly higher than in women with FIGO stage I (p = 0.003) and FIGO stage III (p = 0.02)." (PMID 25647263, 2015).
ovarian carcinoma (continued). "The peritoneal fluid CCL22 concentrations were significantly higher in epithelial ovarian cancer (EOC) patients than in patients with benign tumors-serous cystadenoma (n = 32)." (PMID 25647263, 2015). "The study was undertaken to evaluate macrophage-derived chemokine (CCL22) levels in the peritoneal fluid (PF) and plasma of patients with ovarian cancer (n = 93) in relation to regulatory T cells (Tregs; n = 75)." (PMID 25647263, 2015). "The PF CCL22 levels in patients with FIGO stage I of ovarian cancer were significantly higher than in women with FIGO stages II and III (p < 0.05)." (PMID 25647263, 2015). "The results of the present study show for the first time positive relationship between triple stained CD4+CD25highFoxP3+ cells and concentration of CCL22 chemokine in the peritoneal fluid of patients with ovarian cancer." (PMID 25647263, 2015). "We demonstrated that the plasma CCL22 concentrations are the highest in patients with FIGO stage IV of ovarian cancer." (PMID 25647263, 2015). "CCL22 levels detected in the peritoneal fluid of women suffering from ovarian cancer were found to be significantly higher (p = 0.00002) than in the plasma." (PMID 25647263, 2015). "CCL22 levels detected in the peritoneal fluid of women suffering from ovarian cancer were found to be significantly higher (p < 0.001) than those with benign ovarian disease." (PMID 25647263, 2015). "Blockade of CCL22 in vivo significantly reduces human TReg cells trafficking to tumors in ovarian carcinoma." (PMID 22481922, 2012). "Studies with human ovarian cancers have shown that Treg-cells traffick to the tumor mass and ascites via chemokine receptor CCR4 responding to CCL22 released by tumor cells and tumor-associated macrophages (TAMs)." (PMID 21559338, 2011). "In human ovarian cancer, chemokine, known as CCL22, is produced by macrophages." (PMID 39123373, 2024). "Macrophage production of CCL22 was also observed in human ovarian cancer." (PMID 37445941, 2023). "In some cancers, an increased expression of CCR4 ligands (CCL17 and CCL22) in a tumor may play an anti-tumor role in colon carcinoma, lung cancer, ovarian cancer and melanoma, resulting in an increase in CD4+ T cells and CD8+ T cells." (PMID 33182504, 2020). "Moreover, the ovarian cancer microenvironment can induce migration of CTLA4+ FOXP3+ GITR+ Tregs via the chemokine CCL22 and its receptor CCR4, the latter expressed by infiltrating Tregs." (PMID 28929459, 2018). "In 2004, CCL22 was identified as a Treg attracting chemokine in ovarian cancer." (PMID 30572845, 2018). "Previous studies in mouse or human ovarian cancers suggested that TI Tregs could be recruited from the circulation to tumors by CCL22 and CCL28." (PMID 28290464, 2017). "Blockade of CCL22 in vivo significantly reduced human Treg migration in ovarian carcinoma." (PMID 29037250, 2017). "Blockade of CCL22 in vivo significantly reduced human TReg cell trafficking to ovarian carcinomas." (PMID 23533029, 2013). "Targeting macrophages is a promising therapeutic approach to ovarian cancer and early encouraging work indicates that CSF-1R blockade, anti-B7-H4 scFvs and anti-CCL22 mAbs may generate potent antitumor responses, which is associated with elimination of regulatory T cells." (PMID 26077607, 2015). "CCL22 might be also important for the immunology of ovarian cancer." (PMID 25647263, 2015). "Other chemokines, including CCL3, CCL4, CCL8, and CCL22 (macrophage-derived chemokine), have been detected in ovarian tumors and high levels of CXCL8 and CCL18 have also been found in ascitic fluids from patients with ovarian carcinoma." (PMID 24723924, 2014). "Downregulation of MIF in ovarian cancer cells led to a decrease in the production of cytokines important in TAM recruitment such as CCL2 and CCL22 in vitro and an increase in survival and decrease in ascites in vivo." (PMID 24936477, 2014).
ovarian carcinoma (continued). "Studies with human ovarian cancers have revealed that Treg-cells home to the tumor mass and ascites via CCR4 in response to tumor cell- and TAM-derived CCL22." (PMID 21559338, 2011). "Following co-culture with ovarian cancer cells, macrophages develop a cell-surface phenotype similar to TAMs isolated from human ovarian tumors and a significant increase in genes such as CCL2, CCL22, TNFα, TGFβ1, and VEGF." (PMID 24936477, 2014). "In this same ovarian cancer model, IL-2 treatment was shown to up-regulate CCR4 as well as CXCR4, which further enhanced the ability of Treg to migrate to the tumor microenvironment based on its elevated levels of the Treg ligands CCL22 and CXCL12." (PMID 22112546, 2011).
atopic dermatitis (30 papers, 2011 to 2025). "CCL17 and CCL22 have been reported closely associated with Th2 cell-mediated inflammatory diseases such as atopic dermatitis." (PMID 34451592, 2021). "Rs4359426, a variant of CCL22, has been shown to associate with over-expression of CCL22 mRNA and susceptibility to atopic dermatitis in a gain-of-function manner." (PMID 29156846, 2017). "Although it is unclear whether higher mRNA expression is influenced by altering expression enhancer activity or mRNA stability, polymorphisms in the CCL22 gene appear to be a genetic component of the pathologic mechanisms leading to atopic dermatitis, putatively via increased CCL22 mRNA expression." (PMID 22125604, 2011). "Co-expression of CCL17 and CCL22 has been reported in human type 2 diseases such as in the bronchoalveolar fluid of asthmatics and serum of atopic dermatitis patients." (PMID 41159038, 2025). "Patients with acute myofascial pain have higher levels of CCL22, and in atopic dermatitis, increasing serum CCL17 correlates with increasing pain." (PMID 41291326, 2025). "TNF-α has been reported to promote the production of CCL17 and CCL22 in keratinocytes, inducing features similar to atopic dermatitis." (PMID 38533495, 2024). "The main pathogenic factor in atopic dermatitis (AD) is Th2 inflammation, and levels of serum CCL17 and CCL22 are related to severity in AD patients." (PMID 37110740, 2023). "In the studies concerning MDC/CCL22 in autoimmune diseases and atopic dermatitis (AD), it shows prominent increase." (PMID 37685890, 2023). "There was also an increase in the expression of eosinophils, mast cells, Th2 cells, CCL17, and CCL22 in atopic dermatitis." (PMID 36555280, 2022). "Increased CCL22 expression has been observed in allergies and inflammatory skin responses in the lungs of patients with allergic asthma and atopic dermatitis." (PMID 36555280, 2022). "We have shown that H4R antagonists inhibit the production of the Th2 chemokines CCL17 and CCL22 in human monocyte-derived Langerhans cells from patients with atopic dermatitis." (PMID 36275674, 2022). "In prior studies, chemokines such as CCL17 and CCL22 were suggested as potential therapeutic targets for chronic skin inflammation, including atopic dermatitis." (PMID 34451592, 2021). "CCL17 and CCL22 are key chemokines inducing Th2 chemotaxis and are strongly elevated in the serum of patients with Th2-driven atopic dermatitis." (PMID 34721430, 2021). "Consistently, we and others have also shown that the CCR4 ligands CCL17 and CCL22 are highly expressed in allergic diseases such as atopic dermatitis and bronchial asthma." (PMID 34771703, 2021). "Chronic inflammatory skin diseases, such as atopic dermatitis, are caused by the accumulation of immune cells and the overproduction of chemokines, including CCL17 and CCL22, due to the activation of pro-inflammatory cytokines secreted from keratinocytes." (PMID 34451592, 2021). "In particular, we and others have shown that the levels of CCL17 and CCL22 in the blood are highly elevated in patients with atopic dermatitis and correlate well with disease severity and treatment response." (PMID 34771703, 2021). "First, HaCaTs were used to verify the mRNA expression regulation activity of CCL17 and CCL22, which are biomarkers of atopic dermatitis." (PMID 34451592, 2021). "MDC/CCL22 is a prototypic chemokine expressed selectively on Th2 cells and intimately involved in Th2-skewed allergic diseases, such as atopic dermatitis." (PMID 22919411, 2012). "CCL22 is upregulated in lesional atopic dermatitis skin compared with healthy skin, and keratinocytes in the epidermal layer of AD skin express CCL17 and CCL22." (PMID 22125604, 2011). "Strong positive correlations between the levels of CCL17, CCL22, and total IgE in serum of patients with AD and SCORing Atopic Dermatitis (SCORAD) have also been reported." (PMID 22125604, 2011).